RACK1 (receptor for activated C kinase 1)
Diseases named in the same sentence as RACK1 in open-access papers (continued):
Sharing a sentence is not in itself a finding about the gene and the disease.
tumor (continued). "In vivo experiments further demonstrated that overexpression of RACK1 and USP5 alleviated the inhibitory effects of LRP11 knockdown on tumor proliferation, confirming their crucial role in mediating LRP11-driven HCC growth." (PMID 39891099, 2025). "By mediating the ubiquitination and degradation of the scaffolding protein RACK1, UBE2T hyperactivates the Wnt/β-catenin pathway, thereby promoting tumor growth." (PMID 39791716, 2024). "RACK1 can bind to cyclic adenosine monophosphate, AKT, Src, stratified proteins, and other molecules to regulate tumor cell growth, proliferation, migration, and the cell cycle through multiple signaling pathways." (PMID 38831394, 2024). "In the recurrence of HCC, NUSAP1 can enhance tumor stemness by stimulating STAT3 nuclear translocation and RACK1 activation." (PMID 38441732, 2024). "For instance, the receptor for activated C-kinase 1 (RACK1), a scaffold protein that participates in many intracellular signal transduction pathways, facilitates tumor invasion and lymphatic tube formation." (PMID 37234990, 2023). "In xenograft experiments, it was consistently demonstrated that RACK1 overexpression reversed the effects of ectopic SMURF2 expression and promoted tumor development and metastasis." (PMID 37828084, 2023). "We previously found that the adaptor protein RACK1 interacts with FGFR and consequently promotes the phosphorylation of PKM2 by FGFR16, thereby increasing tumor cell glycolysis." (PMID 33710818, 2021). "In the in vivo experiments, RACK1 knockdown inhibited the in vivo tumorigenesis of NCI-H226 and H1703 cells, as shown by the tumor size and tumor weight." (PMID 33710818, 2021). "To further corroborate our conclusion, we carried out electron microscope (EM) analysis to investigate the ultrastructure of MB tumor cells in both SHH‐MB and Rack1 deletion rescued mice." (PMID 34480519, 2021). "This is exactly what we observe in MCF7 cells where the anti-tumor action of testosterone-BSA is OXER1 and RACK1 dependent." (PMID 33311444, 2020). "We performed further quantitative correlation studies between the expression levels of OXER1/RACK1 mRNAs and the following parameters: age of diagnosis, ER-positivity, PR-positivity, HER2-positivity, incidence of relapse (new tumor event) and tumor stage." (PMID 33311444, 2020). "mRNA and protein levels of both RACK1 and MCM7 were higher in tumor tissue than in the normal lung counterparts." (PMID 28465488, 2017). "Combined inhibition of KIT and RACK1 inhibited growth in imatinib-resistant GIST cell lines and reduced tumor relapse in GIST xenografts." (PMID 26893362, 2016). "To establish the clinical relevance of RACK1 expression in imatinib resistance, we assessed RACK1 expression in 13 GIST patients who had paired tumor specimens available from before and after imatinib treatment (primary vs. relapsed lesions)." (PMID 26893362, 2016). "Combining RACK1 depletion with imatinib synergistically inhibited GIST growth and decreased relapsed tumor growth." (PMID 26893362, 2016). "To examine this possibility, we utilized two siRNAs (siRNA 1 and siRNA 2) specific for different regions of the RACK1 mRNA to knockdown RACK1 expression in mock and MRV infected normoxic and hypoxic tumor cells." (PMID 24504474, 2014). "RACK1 also binds the β subunits of integrin and integrates and facilitates signaling between the IGF-IR and integrins during tumour cell migration." (PMID 21978545, 2011). "We suggest that the transcription factors SMAD3/4, GNB2L1/RACK1, MYC, MAX and JUN, whose functions have been extensively studied in tumours but only marginally in muscle, appear instead to play important roles in regulating muscle response to atrophy." (PMID 19108710, 2008). "Other studies reported the axis of syntaxin 6/USF2/LC3B which promoted autophagy flux and tumour progression in HCC, showing that syntaxin 6 could trigger autophagy and affect the RACK1/STAT3 axis." (PMID 40293576, 2025).
tumor (continued). "In addition, RACK1 interacted with GNA14, which led to reductions in the MAPK/JNK and PI3K/AKT pathways, contributing to the inhibition of tumor progression in HCC." (PMID 39199296, 2024). "While RACK1 is also involved in cell polarity and chemotaxis in tumor cells, there is no direct evidence that RACK1 regulates polarity and chemotaxis of the activated microglia." (PMID 38410996, 2024). "In addition, we extracted tumour tissue proteins for experiments, and the results showed that SBSGL inhibited the O‐GlcNAcylation of RACK1 protein and reduced its expression level, validating the results of the cellular experiments." (PMID 38451046, 2024). "And IHC staining of OTUB1, KI67, RACK1, p-ERK, p-AKT, and p-FAK supported that efficient OTUB1 knockdown ameliorated the hyperactivation of the oncogenic pathway, and corroborated the reduced subcutaneous tumor growth when OTUB1 silenced." (PMID 38315284, 2024). "To further investigate the role of RACK1 in tumor growth in vivo, we established xenograft models in BALB/c nude mice by subcutaneous injection of control and RACK1-silenced MDA-231 cells, as well as RACK1-rescued cells." (PMID 37848434, 2023). "With little degradation, excess CCDC102B binds with RACK1, which may compete with IKK binding, resulting in NF-κB pathway activation and eventually promoting tumor development or metastasis." (PMID 35957886, 2022). "In conclusion, we demonstrated that the levels of Rack1 were upregulated in majority of MB tumor samples, and genetic ablation of Rack1 in SHH‐MB tumor mice significantly reduced MB proliferation, reduced the tumor size, and prolonged the survival of tumor rescue mice." (PMID 34480519, 2021). "Genetic ablation of Rack1 expression in SHH‐MB tumor mice could significantly inhibit MB proliferation, reduce the tumor size, and prolong the survival of tumor rescue mice." (PMID 34480519, 2021). "RACK1 may also be regulated by YY1, indicating wider interactions with factors known to regulate the tumour microenvironment, including the melatonergic pathway." (PMID 33375613, 2020). "Importantly, overexpressed miR-302b-3p, miR-302c-3p or miR-302d-3p or RACK1 enhanced the apoptosis and suppressed the proliferation of CSCC cells in vitro, while inhibiting tumor growth in vivo by targeting CCNO." (PMID 32792866, 2020). "Our results showed that the downregulation of RACK1 expression inhibited the proliferation, migration, and invasion of HCT116 cells, further confirming that RACK1 may act as a tumor promoter in CRC." (PMID 30962803, 2019). "Moreover, both RACK1 and MCM7 levels were positively correlated with histological grade, lymphatic metastasis, and tumor TNM stage." (PMID 28465488, 2017). "After 14 days, when established GIST-882 subcutaneous tumor xenografts were detectable, mice were treated for 8 weeks with imatinib with or without RACK1 shRNA." (PMID 26893362, 2016). "Taken together, these results indicate that deletion of Rack1 in SHH‐MB tumor cells could significantly inhibit the proliferation of MB tumor cells rather than the induction of the MB tumor cell death." (PMID 34480519, 2021). "Our data also suggest that Rack1 is not only essential for GNPs proliferation and migration at postnatal cerebellar developmental stage, which may also play an important role in enhancing SHH‐type MB tumor formation by positively regulating the expression and function of Gli1 and HDAC2." (PMID 34480519, 2021). "Given that SHH signaling was significantly suppressed in Rack1‐deficient GNPs,24 and deletion of Rack1 in SHH‐MB could significantly suppress the proliferation of tumor cells, therefore, we asked whether the absence of Rack1 in MB tumor cells could also induce the inactivation of SHH signaling." (PMID 34480519, 2021).
tumor (continued). "Moreover, the signaling hub protein RACK1 (Receptor for Activated C Kinase 1), a relevant EDC target that responds to steroid-active compounds, could be considered a molecular bridge between the endocrine-regulated tumor microenvironment and the innate immune system." (PMID 41012423, 2025). "Besides, although NP69 is an immortalized nasopharyngeal epithelial cell, it is a relatively normal cell line compared with tumor cell, so maybe it can not fully reflect the physiological characteristics of RACK1 expression in normal nasopharyngeal epithelial tissues." (PMID 27170279, 2016).
infection (23 papers, 2011 to 2025). The state of being infected such as from the introduction of a foreign agent such as serum, vaccine, antigenic substance or organism. "Here, we provide in vivo evidence that loss of RACK1 led to impaired Tfh cell development and function during P. yoelii 17XNL infection." (PMID 39024388, 2024). "In contrast, RACK1 expression is downregulated during infections with other viruses, including CSFV and Epstein–Barr virus." (PMID 41395239, 2025). "The protein level of RACK1 was strikingly elevated in splenic CD4+ T cells within 5 days of infection, implying a biological relevance of this molecule with CD4+ T cell activities and functions." (PMID 39024388, 2024). "RACK1 protein and mRNA expression levels were significantly decreased by infection with different MOIs of P. multocida at 24 h post-infection (hpi)." (PMID 37684678, 2023). "The immunofluorescence staining results showed that RACK1, NLRP3 and NEK7 were diffusely distributed in the cytoplasm in uninfected cells, while PmCQ2 infection induced the colocalization of RACK1 with NLRP3 and NEK7 (white arrows)." (PMID 37684678, 2023). "LCDV-, VDAC2-, and RACK1-positive green signals were also widely distributed at 2 h post-infection; the merging of CTB images with LCDV, VDAC2, and RACK1 images revealed many yellow co-localization signals in the cell membrane and cytoplasm." (PMID 32630682, 2020). "Then, we rescued Rack1 expression in Rack1-silenced cells through infection of lentivirus expressing Flag-tagged Rack1WT and Src binding-deficient Rack1Y246F mutant." (PMID 31113450, 2019). "During the whole experimental time period (from 1 hour to 60 hours), substantial increase of cellular RACK1 mRNA (uninduced levels highlighted by the red line) and protein was observed, compared with the non-infection control." (PMID 29445214, 2018). "Here we demonstrated that infection of Marc-145 cells with the highly pathogenic PRRSV strain YN-1 from our lab led to activation of NF-κB and upregulation of RACK1 expression." (PMID 29445214, 2018). "Apart from genes encoding TFs, a number of genes encoding signalling functions including G-proteins (GH3-2, OsGH308, OsRacB and Rack1) and kinases (Xa26, OsMPK5) have also been shown to have a functional role in response to infection." (PMID 23398910, 2013). "Wounding and infection require G-protein signaling, involving the Gα protein GPA-12 and the Gß RACK-1, while infection specifically involves the Tribbles-like kinase NIPI-3." (PMID 22470487, 2012). "Further, a yopK mutant unable to bind RACK1 shows an avirulent phenotype during mouse infection, suggesting that RACK1 targeting by YopK is a requirement for virulence." (PMID 21347310, 2011). "More importantly, we elucidate an indispensable role for RACK1 in Tfh cell differentiation and maintenance, which is crucial for germinal center formation, parasite-specific antibody production, and host resistance to P. yoelii 17XNL infection." (PMID 39024388, 2024). "Next, we dissected the effects of RACK1 on CD4+ T cell responses after P. yoelii 17XNL infection." (PMID 39024388, 2024). "Moreover, although contracted CD4+ T cell population was found as the infection progressed (e.g., day 16 p.i.), RACK1 KO mice exhibited a persistently lower proportion and overall number of CD4+ T cells in the spleen, as compared with those in WT mice." (PMID 39024388, 2024). "It has been reported that the expression of RACK1 could be regulated by infection with different pathogens, such as M.tb, Helicobacter pylori, porcine reproductive and respiratory syndrome virus (PRRSV), Zika virus and hepatitis C virus." (PMID 37684678, 2023). "Furthermore, endogenous coimmunoprecipitation experiments showed that PmCQ2 infection induced the interaction of RACK1 with NLRP3 and NEK7 in macrophages." (PMID 37684678, 2023). "In addition, RACK1 expression is significantly upregulated during infection with various pathogens, including M.tb and PRRSV." (PMID 37684678, 2023).
infection (continued). "In addition, we also upregulated RACK1 expression in MDA-231 and SK-BR-3 cells by using lentiviral infection and found that elevated RACK1 promoted cell proliferation." (PMID 37848434, 2023). "Moreover, RACK1 inhibited the attachment and invasion of PmCQ2 in host cells to reduce infection, indicating that RACK1 serves as a positive regulator of the host defences against P. multocida infection, but the detailed mechanism needs to be further studied." (PMID 37684678, 2023). "Arabidopsis receptor for activated C kinase 1 (encoded by RACK1) functions as a MAPK scaffold protein in the absence of pathogen infection." (PMID 37653969, 2023). "RACK1 is a candidate interacting protein for establishing infection of Bombyx mori cypovirus." (PMID 35444625, 2022). "Similarly, HCV RNA levels were reduced in the RACK1-depleted cells, and best detectable 3 days post-infection." (PMID 31525236, 2019). "Therefore, HSV-1 infection induces the production of RACK1 at very early time points after infection and the level of RACK1 upregulation is dependent on viral dose." (PMID 31143369, 2019). "For example, it has been discovered that RACK1 (receptor for activated C kinase) is phosphorylated in a B1 dependent manner, triggering a selective advantage for translation of viral RNAs that is postulated to enhance viral fitness late in infection." (PMID 30768651, 2019). "However, we also observed an early increase of RACK1 mRNA production following PRRSV infection (1 hpi), while RACK1 protein levels remain constant throughout the period of infection." (PMID 29445214, 2018). "The cells were transfected with siRNAs, challenged with PRRSV 48 hours post transfection, fixed 24 hours or 48 hours post infection and immunofluorescently stained to visualize the nuclei (blue channel) and the expression level of RACK1 (red channel) and viral N protein (green channel)." (PMID 29445214, 2018). "To ascertain whether RACK1 is involved in phagocytosis of Y. pseudotuberculosis or if it interferes with antiphagocytosis, we performed infection experiments using RACK1 RNAi cells and determined the amount of extracellular and intracellular bacteria." (PMID 21347310, 2011). "Initial western blot analysis showed that the protein expression level of RACK1 was downregulated in both BHK‐21 and PK‐15 cells at 24 h post infection (hpi) with PRV." (PMID 41395239, 2025). "Consistent with the requirement for RACK1 in conventional T cell proliferation in vitro, we observed that deletion of RACK1 led to a remarkably reduced proportion and absolute number of splenic CD4+ T cells at day 7 post-infection (p.i.)." (PMID 39024388, 2024). "Together, these data demonstrate that RACK1 is required for P. yoelii-primed activation and expansion of CD4+ T cells, and exerts a beneficial effect on Th1, Th17, and nTreg cell expansion during the early phase of infection." (PMID 39024388, 2024). "Consequently, these RACK1-deficient mice could not recover from the normally non-lethal infection." (PMID 39024388, 2024). "Consequently, RACK1 in CD4+ T cells contributes significantly to germinal center formation, parasite-specific IgG production, and host resistance to the infection." (PMID 39024388, 2024). "This means two things; firstly, translocation of effectors and the process of cytotoxicity induction do not require RACK1, and secondly, antiphagocytosis and cytotoxicity are clearly two distinct events during cell infection." (PMID 21347310, 2011). "However, in IBV-infected Vero cells, a proportion of endogenous RACK1 was dispersed into the cytoplasm at 6 h.p.i. and 12 h.p.i., where it co-localized with IBV N protein, indicating alterations in its localization by N protein during infection." (PMID 39602452, 2024).
infection (continued). "Furthermore, RACK1 knockdown significantly decreased the P1/7-induced phosphorylation of P65, which is similar to the effect of treatment with the NF-κB inhibitor BAY, suggesting that RACK1 mediates the phosphorylation of P65 during P1/7 infection." (PMID 39334337, 2024). "Furthermore, knockdown of RACK1 significantly inhibited the secretion of IL-1β and TNF-α as well as the transcription of NLRP3 and IL-1β during PmCQ2 infection." (PMID 37684678, 2023). "Particularly, we identified a novel role of RACK1 in orchestrating the Tfh polarization program and subsequent germinal center reaction, which contributes to the development of functional antibodies and ultimately immune resistance to non-lethal blood-stage P. yoelii 17XNL infection." (PMID 39024388, 2024). "Interestingly, cells depleted of RACK1, a component of the 40S subunit, leads to inhibition of 5′UTR IRES but not IGR IRES translation during infection, thus further supporting that the two CrPV IRESs are differentially regulated at the ribosome level." (PMID 26797630, 2016).
neurodegenerative disease (5 papers, 2021 to 2025). A disorder of the central nervous system characterized by gradual and progressive loss of neural tissue and neurologic function. "Neuron with Imbalanced Signaling: Persistent shift toward free, dimeric RACK1 forms incapable of supporting translation may underlie impaired synaptic plasticity in neurodegenerative diseases such as Alzheimer’s, where disrupted membrane association and function of RACK1 have been observed." (PMID 41373878, 2025). "Therefore, we suggest that RACK1 might play a role in SG-regulated RNA metabolism/protein synthesis in neurons, and that such functions might play a part in many neurodegenerative diseases." (PMID 36010666, 2022). "In this context, the receptor for activated C kinase 1 (RACK1) emerges as a possible bridge between translational impairment and SGs, thanks to its ribosome-related functions and its role in the neurodegenerative diseases here considered." (PMID 36010666, 2022).
bacterial infection (1 paper, 2023). "Next, to investigate whether RACK-1-mediated cell viability is associated with the amount of bacterial infection, the numbers of adherent and invasive PmCQ2 bacteria were counted at 3 and 7 hpi, respectively." (PMID 37684678, 2023).
intestinal diseases (1 paper, 2024). "In intestinal diseases, Rack1 regulates E‐cadherin endocytosis induced by Src and growth factors, maintaining intestinal epithelial cell connection stability." (PMID 38523594, 2024).
RACK1 also shares sentences with these, for which no sentence is quoted: pancreatic ductal adenocarcinoma (4 papers); Cardiovascular disease (3); diabetic nephropathy (3); hepatoblastoma (3); multiple myeloma (3); squamous cell carcinoma (3); chronic obstructive pulmonary disease (2); endometriosis (2); gastrointestinal stromal tumor (2); influenza (2); Machado-Joseph disease (2); pancreatic cancer (2); triple-negative breast carcinoma (2); acute megakaryoblastic leukemia (1); acute pancreatitis (1); acute respiratory distress syndrome (1); adenocarcinoma (1); Anxiety (1); bipolar disorder (1); brain trauma (1); breast tumor (1); cervical intraepithelial neoplasia (1); cervicitis (1); Cirrhosis (1); cognitive decline (1); colitis (1); colon adenocarcinoma (1); colonic adenomas (1); colonic inflammatory polyps (1); colorectal adenocarcinoma (1).
A further 27 diseases each share a sentence with RACK1 in 1 paper.